DPP4 (dipeptidyl peptidase 4)
Diseases named in the same sentence as DPP4 in open-access papers (continued):
Sharing a sentence is not in itself a finding about the gene and the disease.
Obesity (continued). "How DPP-4 inhibitor attenuates the activation of the S6K1 in the setting of overnutrition- and obesity-induced INS resistance as well as its relation to β-cell function is yet fully elucidated." (PMID 30116740, 2018). "This study revealed pleiotropic protective effects of DPP-4 inhibitor SIT on cardiac function, glycemia, and β-cell function together with reducing S6K1 activation and IRS-1 and IRS-2 degradation in the obesity female mouse model." (PMID 30116740, 2018). "Our present results also suggested that DPP-4 inhibits FGF-2/EGR-1/VEGF-A signaling to promote cardiac capillary rarefaction and cardiac dysfunction in mice with dietary obesity." (PMID 28771625, 2017). "DPP-4 release is strongly correlated with adipocyte size, potentially representing an important source of DPP-4 in obesity." (PMID 27652270, 2016). "Recently, dipeptidyl peptidase 4 (DPP4; also known as CD26, EC3.4.14.5) was identified as a novel adipokine potentially linking obesity to metabolic syndrome." (PMID 26633898, 2015). "Altered expression of soluble DPP4 is commonly seen in many disorders such as solid tumors, autoimmune diseases, hepatitis C, type 2 diabetes (T2DM), and obesity." (PMID 26075284, 2015). "However, the correlations we found suggest that DPP-4 and NPY family peptides in small intestine muscular tissue are related to GI symptoms in patients with obesity or obesity and T2DM." (PMID 40142315, 2025). "Another DPP-4 inhibitor, sitagliptin, has been shown to decrease LV cardiomyocyte Fpassive and enhance global LV performance due to elevated cGMP levels, PKG activity, and improved titin phosphorylation in a mouse model of obesity and DM." (PMID 40361188, 2025). "Such an analysis would have provided valuable insights into the changes of NPY family peptides and DPP-4 content within the jejunal muscular tissue of patients without obesity and T2DM." (PMID 40142315, 2025). "For example, dipeptidyl peptidase 4 (DPP‐4) resistant synthetic analogues of the naturally occurring GLP‐1 hormone have gained significant attention in recent years for their role in weight management and obesity treatment." (PMID 39417406, 2024). "Of the patients who received a DPP-4 inhibitor, 41.90% had hypertension, 17.32% had hyperlipidemia, 8.38% had CAD, 4.90% had arrhythmia, 3.08% had heart failure, 1.75% had CKD, and 0.49% had obesity." (PMID 39177655, 2024). "While more research is needed to understand the role of DPP-4 in GDM, the existing literature suggests that DPP-4i (i.e., gliptin) therapy could help mitigate the capacity of GDM to program the fetus for future obesity and metabolic disease." (PMID 38339106, 2024). "Investigating the pathophysiological roles of PDGFRA+ DPP4- nonadipogenic niche cells (AFECs) in obesity-induced insulin resistance and metabolic dysfunction would be worthwhile." (PMID 39465352, 2024). "We additionally examined circulating DPP4 levels and the mRNA abundances of sheddases in a mouse model of severe metabolic liver disease without obesity, phosphatidylethanolamine N-methyltransferase (Pemt–/–) mice." (PMID 36472923, 2023). "DPP‐4 is present in visceral fat, contributing to insulin resistance and adipocyte inflammation, so that DPP‐4i might correct some of the factors linking obesity with poor outcomes." (PMID 36690377, 2023). "Both DPP4 and ACE1 metabolize peptides on the extracellular milieu, suggesting that in females, conversely to males, the extracellular peptide metabolism plays a major role in diet-induced obesity." (PMID 37894869, 2023). "The present finding that exenatide lowers DPP-4 levels is important because circulating DPP-4 levels are elevated in obesity, regardless of glucose tolerance." (PMID 38027106, 2023). "Furthermore, DPP4 plays a role in SARS-CoV-2 infection as a co-receptor, and sDPP4 levels are upregulated in obesity and T2DM, possibly complicating disease outcomes, if these patients acquire COVID-19." (PMID 35331159, 2022).
Obesity (continued). "This suggests that DPP4 could have an important participation in the chronic low-grade inflammation present in dyslipidemias, T2DM, IR, obesity, and atherosclerosis." (PMID 34178021, 2021). "Indeed, it has been reported that obesity is a greater driver of treatment options when comparing SGLT2i, GLP-1 RA, and dipeptidyl peptidase 4 inhibitors." (PMID 33990175, 2021). "Because GRK2 levels and activity have been reported to be enhanced in obesity and insulin resistance, in future studies it will be important to evaluate whether GRK inhibition enhances the effect of DPP-4." (PMID 34054727, 2021). "Although the cardiovascular safety of DPP-4 inhibitors has been proven in T2DM, the net effect of these drugs on leptin concentrations in obesity-related disease remains unclear." (PMID 34446063, 2021). "Last but not least, DPP-4 levels are significantly increased in the blood of patients with obesity and obesity-induced metabolic syndrome, and these comorbidities can aggravate the outcome of patients with COVID-19." (PMID 34015003, 2021). "Second, we did not study the relationships between DPP4 inhibition, sDPP4 and inflammation, in people with severe obesity, or those with pre-existing inflammatory conditions such as people with acute infections." (PMID 32724076, 2020). "We hypothesize that enhanced circulating levels of soluble DPP4 and misbalanced ACE2 expression found in obesity and T2DM may contribute to the severity of COVID-19 related to these disease/comorbidities." (PMID 32848769, 2020). "On the other hand, T2DM is often associated with increased body mass index (BMI), and other studies have suggested that levels of plasma DPP-4 activity actually correlate better with clinical parameters of obesity rather than of T2DM and glucose per se." (PMID 30828317, 2019). "Combining both the studies we show that plasma DPP4 activity is significantly increased in T2DM population irrespective of obesity pointing out to the fact that adipose-derived DPP4 has no major contribution on plasma DPP4 activity." (PMID 31402899, 2019). "In this study, we explored whether DPP-4 inhibitor sitagliptin (SIT) is involved in the protection of cardiac function and β-cell function using an obesity female mouse model." (PMID 30116740, 2018). "Our previous work has demonstrated a role of DPP-4 non-enzymatic function in regulating dendritic cell (DC)/macrophage-mediated adipose tissue inflammation in obesity." (PMID 29270177, 2017). "Furthermore, recent animal studies with DPP4 inhibitors support the notion that DPP4 may play a functional role within adipose tissue, because DPP4 inhibition has been seen to prevent adipose tissue inflammation and development of glucose intolerance in high fat diet induced obesity in mice." (PMID 26983599, 2016). "Second, the increased DPP-4 activity was reported in T2DM when accompanied with a significant degree of insulin resistance (IR), i.e., DPP-4 was recently proposed as a novel adipokine linking obesity to metabolic syndrome (MS)." (PMID 27006706, 2016). "DPP4 is upregulated in proinflammatory states including T2DM and obesity." (PMID 27111895, 2016). "Mice lacking DPP4 (Dpp4−/−) are protected from the development of diet-induced obesity and demonstrate improved postprandial glucose control." (PMID 26075284, 2015). "Associations between DPP-4 inhibitor use and suicidal behaviors were similar to those obtained for GLP-1 RA, including after stratification according to the presence or absence of a recent psychiatric history and obesity." (PMID 39844933, 2025). "DPP-4 inhibitors cases, compared to GLP-1 RA cases, were older (mean age 62.5 years vs. 57.4 years, respectively), more often male (51.5% vs. 44.6%), had lesser history of recent psychiatric disorders (56.7% vs. 67.7%), and had lesser history of obesity (23.5% vs. 51.3%)." (PMID 39844933, 2025).
Obesity (continued). "DPP-4 inhibitors are widely used in clinical practice as oral antidiabetic agents and may also improve gut barrier function via GLP-2-dependent mechanisms in murine obesity models." (PMID 40723884, 2025). "Additionally, DPP-4 exert non-catalytic functions, including the reduction in dendritic cell/macrophage-mediated adipose tissue inflammation in obesity by affecting macrophage migration (CD11b+, CD11c+, and Ly6Chi)." (PMID 40566497, 2025). "Mice lacking the DPP4 gene were difficult to develop obesity after a high-fat diet." (PMID 38003291, 2023). "Moreover, incretin-based therapies, such as treatment with dipeptidyl peptidase 4 (DPP-4) inhibitors, which might impact autophagy, are considered as critical approaches for the treatment of obesity." (PMID 37876013, 2023). "Notably, systemic DPP4 activity was increased 4-fold relative to controls, suggesting dysregulation of hepatic lipid pathways is related to increased DPP4 activity, independent of the development of obesity." (PMID 36472923, 2023). "We could not rule out the possibility that several factors, such as CVD history, race, and the presence or absence of obesity, differentially impact the effect of DPP-4 inhibitors on CVD." (PMID 37669959, 2023). "Hepatocyte DPP4 expression in obesity has been demonstrated to increase the level of soluble DPP4 in serum and promote visceral adipose tissue (VAT) inflammation and insulin resistance, suggesting that crosstalk between the liver and VAT can exacerbate metabolic disorder in the context of obesity." (PMID 35053615, 2022). "Similarly, mice lacking the DPP4 gene were refractory to the development of obesity after a high-fat diet, in relation to a combination of reduced energy intake and concomitant increased energy expenditure." (PMID 36140405, 2022). "Thus, our overall findings point toward a role for DPP4 in identifying NAFLD and metabolic diseases in individuals with and without obesity and T2DM, instead of being associated with fat mass and body adiposity itself." (PMID 32852705, 2021). "Additional mechanisms driven by obesity include gut epithelial lymphocytes sequestering GLP-1, decreased availability of GLP1-secreting enteroendocrine L cells, or lymphocyte-driven upregulation of the expression of molecules (dipeptidyl peptidase 4 (DPP4)) degrading GLP1." (PMID 35052763, 2021). "However, the physiological inhibitory control of GLP-1 and its accelerated inactivation by plasma dipeptidyl-peptidase 4 (DPP4) hyperactivity suggests that the impaired secretion and/or activity of GLP-1 may be involved in the pathogenesis of obesity." (PMID 32121057, 2020). "To further confirm the hypothesis that plasma DPP4 activity is independent of obesity, we conducted a follow-up study with 20 obese patients (T2DM = 4 and non-T2DM = 16) undergoing MGB." (PMID 31402899, 2019). "Previous studies have documented that circulating DPP4 originates from differentiated adipocytes and could be a novel adipokine that potentially links obesity to the metabolic syndrome." (PMID 29958403, 2018). "Although local production of DPP4 in the liver may be the most biologically relevant source for NAFLD, decreased delivery of adipose-derived DPP4 to the liver could also contribute, possibly interacting with higher incretin delivery during obesity reversal." (PMID 28360082, 2017). "The lowering of DPP-4 levels observed in the present study is in accordance with the maintained GLP-1 levels and may be specific to GLP-1RA exenatide, since liraglutide, with its beneficial metabolic effects, has been shown to suppress endogenous total GLP-1 in adults with obesity." (PMID 38027106, 2023). "Therefore, the main goal of the current study was to evaluate the expression of DPP-4 and NPY family peptides in the small intestine muscular tissue and explore association of these substances with gastrointestinal symptoms among patients with or without T2DM and obesity." (PMID 40142315, 2025).
Obesity (continued). "This study is among the first to investigate DPP-4 and NPY peptides in human jejunal muscular tissue among patients with or without T2DM and obesity." (PMID 40142315, 2025). "The main finding of this study is that individuals with NAFLD have increased plasma DPP4 activity than no-NAFLD subjects, regardless of the presence of obesity and metabolic disease." (PMID 32852705, 2021). "In conclusion, this study demonstrates the coexistence of increased plasma DPP4 concentration and DPP4 enzymatic activity in patients with NAFLD, with and without obesity and metabolic disorders." (PMID 32852705, 2021). "Moreover, DPP4 expression in inflammatory cells such as dendritic cells and macrophages may have a significant role in modulating the adipose tissue inflammation in obesity through its nonenzymatic function." (PMID 34043673, 2021). "It will be of high interest to decipher the roles of DPP4 in mediating SARS-CoV-2 entry as well as in inflammation and immune response in COVID-19 patients with or without obesity." (PMID 32806722, 2020). "In other words, while DPP4+ cells undergo no adipogenic differentiation during normal development, DPP4+ cells undergo adipogenic differentiation under HFD conditions, thereby contributing to hyperplastic expansion of adipose tissue during diet-induced obesity." (PMID 39465352, 2024). "Therefore, aim of this study was to investigate the relationship between hepatic and systemic DPP4 levels/activity and the presence of NAFLD/NASH in individuals with and without obesity and T2DM." (PMID 32852705, 2021). "In conclusion, accumulating studies indicate that DPP4 inhibitors are clinically useful for patients with T2DM accompanied by liver dysfunction based on fatty liver, and that DPP4 inhibition affects liver function regardless of diabetic status and obesity." (PMID 26284071, 2015). "Dipeptidyl peptidase-4 also has nonglycemic effects by controlling the progression of inflammation, which may be mediated more through direct protein-protein interactions than catalytic activity in the context of nonalcoholic fatty liver disease (NAFLD), obesity, and type 2 diabetes (T2D)." (PMID 32231442, 2020).
COVID-19 (196 papers, 2020 to 2026). A disease caused by infection with severe acute respiratory syndrome coronavirus 2. "COVID-19 has also been associated with inflammatory processes involving key mediators such as DPP4 and MMP1, which are known to mediate both tissue remodeling and systemic inflammation." (PMID 40843809, 2025). "This nationwide study provides evidence that DPP-4 inhibitor use in diabetic patients hospitalized with COVID-19 is associated with lower mortality rates." (PMID 40869643, 2025). "Several systematic reviews and meta-analyses have reported mixed results regarding the association between DPP-4 inhibitor use and COVID-19 outcomes." (PMID 40869643, 2025). "Reduced activity of circulating DPP4 has been associated with severe COVID-19 and represents a strong prognostic biomarker of mortality." (PMID 41464188, 2025). "Our multivariable Cox regression analysis, adjusted for potential confounders including age, sex, and comorbidities, showed that DPP-4 inhibitor use was independently associated with reduced COVID-19-related mortality (adjusted HR: 0.455; 95% CI: 0.414–0.499)." (PMID 40869643, 2025). "Consistently, IPTW-adjusted logistic regression confirmed a significant association between DPP-4 inhibitor use and reduced COVID-19-related mortality (OR: 0.30; 95% CI: 0.27–0.34; p < 0.001), reinforcing the robustness of our primary findings." (PMID 40869643, 2025). "The same study reported with high certainty evidence of a decreased risk of COVID-19-related death with the use of DPP-4 inhibitors." (PMID 39526061, 2024). "Synthesizing the findings from the systematic review and meta-analyses reveals that metformin use and DPP-4 inhibitor use are associated with decreased mortality in individuals with DM who were hospitalized for COVID-19." (PMID 39835258, 2024). "There is increased DPP4 expression in airway samples from COVID-19 patients, while its inhibition was associated with lower COVID-19 mortality." (PMID 39205219, 2024). "DPP-4 inhibitors, when administered in the inpatient setting, also seem to reduce the risk of COVID-19-associated deaths by about 50%." (PMID 37064327, 2023). "Another meta-analysis included 4,477 T2DM patients from 9 studies also confirmed that DPP-4 inhibitor use was associated with lower mortality in COVID-19 patients." (PMID 36017317, 2022). "Altogether these data indicate that DPP4 inhibitors have a potential therapeutic value in the multi-organ injury caused by COVID-19." (PMID 36009573, 2022). "The association between decreased serum DPP4 activity and peak COVID-19 severity outcomes is also consistent with the prior report indicating that serum DPP4 activity is decreased in severe sepsis." (PMID 35195023, 2022). "In this review, we analyze the evidence for the role of DPP4 on COVID-19 risk and clinical outcome, and its contribution to COVID-19 physiopathology." (PMID 36009573, 2022). "DPP4 expression was also associated with obesity, and subsequent investigations validated its association with COVID-19." (PMID 36553622, 2022). "In one study, missense and splice acceptor variants in DPP4 (c.95-2A > G, c.796G > A, c.1887 + 3G > A) were reported in COVID-19 patients and related to the severity of the disease." (PMID 36553622, 2022). "Clinical data obtained when using DPP4 inhibitors showed that this protease has an influence on the risk and clinical outcome of COVID-19." (PMID 36009573, 2022). "On the other hand, it has been described that a Neanderthal variant of the DPP4 promoter doubles the risk of being hospitalized for COVID-19, with DPP4 levels correlating with the severity of COVID-19." (PMID 36009573, 2022). "The reduction in serum DPP4 activity among hospitalized patients with acute COVID-19 was associated with increasing clinical severity and was lowest in the group of patients who subsequently died." (PMID 35195023, 2022).